TBK1 (TANK binding kinase 1)
Diseases named in the same sentence as TBK1 in open-access papers (continued):
Sharing a sentence is not in itself a finding about the gene and the disease.
infection (continued). "Consistently, the levels of phosphorylated TBK1 and IRF3 induced by VSVΔM51-GFP infection were decreased in PTK2B-knockdown THP1 cells compared with those in the control cells." (PMID 37989995, 2023). "To do this, we pre-treated mice with 100 mg/kg Amlexanox, a specific inhibitor of TBK1 and its homolog IKKε, for 5 days prior to eGFP-CVB infection and every day following infection." (PMID 36044516, 2022). "Because TBK1 mediates the phosphorylation and nuclear transcription of IRF3 during infection, we also examined activation of IRF3." (PMID 36044516, 2022). "Next, we measured TBK1 K63 ubiquitination in WT and SRA−/− macrophages after VSV or HSV-1 infection." (PMID 36342281, 2022). "The molecular basis of ocular HSV-1 infection has led to the identification of inhibitors of TANK-binding kinase 1 (TBK1) such as BX795, which strongly suppressed infection by multiple strains of HSV-1 in vivo." (PMID 35328532, 2022). "Infection can trigger various pathogen recognition receptor (PRR) signaling pathways, which converge on TBK1-mediated phosphorylation and activation of the IRF3 and IRF7 transcription factors." (PMID 35244540, 2022). "However, for the STING and TBK1 knockout cells, the initial phagocytic capacities (at 6h) were significantly lower than the WT cells and hence the observed lower infection rates might have stemmed from fewer infecting L. major at the beginning." (PMID 36405710, 2022). "Despite the increase in TBK1 phosphorylation, both CHIKV and DENV infections led to a gradual decline in the TBK1 protein level during the course of infection, with the decline being higher in DENV-infected cells compared to CHIKV-infected cells." (PMID 35573775, 2022). "We found that phosphorylation of TBK1 in TRIM18 KO BMDM was significantly enhanced relative to that in WT BMDM after infection with CVB3 or adenovirus, suggesting that TRIM18 indeed recruited PPM1A to dephosphorylate TBK1 for TBK1 inactivation." (PMID 35909127, 2022). "During pathogen infection, pattern-recognition receptors (PRR) allow for the cellular recognition of conserved molecular signatures of microbial PAMPs, which activate TBK1." (PMID 35395857, 2022). "We found that the levels of phosphorylation of TBK1, IRF3 and IκBα were higher in Prmt9CKO macrophages than those of Prmt9WT macrophages after infection with SeV or stimulation with 5’ppp-RNA." (PMID 36028484, 2022). "Significantly, our results showed that the expression of six major adaptor molecules (Myd88, IRAK2, IRAK4, TRAF3, TBK-1 and IRF7) downstream of RNA sensors were dramatically decreased in the PAMs with a PRRSV-ADE infection." (PMID 36680075, 2022). "Immunoblot analyses revealed that STINGPOX infection of primary murine bone-marrow derived DCs (mBMDCs) resulted in increased phosphorylation of STING, TBK1, and IRF3 relative to OncoVACV." (PMID 36713447, 2022). "Phosphorylation levels of TBK1, IRF3, and p65 were significantly lower in FMDV 2B-overexpressed RAW264.7 cells than in the control cells at the indicated time points after the infection." (PMID 36248821, 2022). "We found that ASFV-WT downregulated the expression of TBK1, while the TBK1 expression was significantly increased upon ASFV-ΔA137R infection in PAMs, although it was lower than that in the uninfected PAMs." (PMID 35412346, 2022). "The pretreatment of nasal HAE with BX795, a TANK-binding kinase 1 inhibitor, partially alleviates the reduced replication of SARS-CoV-2 or influenza A(H1N1)pdm09 during sequential infection with both virus combinations." (PMID 35215988, 2022). "This is consistent with the phosphorylation of TBK1 and IRF3 within 30–60 min post infection following the activation of TLR4-TRAM-TRIF signaling." (PMID 35947948, 2022). "Taken together, these results suggest that the cytoplasmic localization of histone H2A is required for the protein degradations of TBK1 and IRF3 and the negative regulation of histone H2A on the SVCV infection." (PMID 34868031, 2021).
infection (continued). "Differential activation of autophagy and MTORC1 by SQSTM1/p62TRM, TBK1, TRAF6 and RALB, which are among the prominent molecules involved in both pathways, needs to be studied further in disease and/or infection-relevant settings." (PMID 32627660, 2021). "Infection of Cyld−/− Dendritic Cells (DC) and Mouse Embryonic Fibroblasts (MEF) with vesicular stomatitis virus (VSV) resulted in hyperactivation of TBK1 and IKKɛ, and consequently hyper-induction of type I IFNs due to increased levels of RIG-I ubiquitination." (PMID 33808506, 2021). "To further investigate the innate immunity pathways regulated by DDX5, we detected the expression of p-TBK1, p-IKKγ, p-p65, and p-IRF7 in DDX5- or METTL3-knockdown or -overexpressing MEFs after infection with VSV." (PMID 33909701, 2021). "Nlrp12−/− BMDCs had increased TBK1 and IRF3 phosphorylation concomitant with increased production of type I IFNs upon infection with VSV or short dsRNA compared to WT cells." (PMID 33808506, 2021). "When TBK1 was inhibited using BX795, both the total level of OPTN and the phosphorylated form were decreased in an infection independent manner suggesting that OPTN function is constitutively regulated by TBK1." (PMID 34518549, 2021). "Taken together, ours and previously published data strongly suggest that both TBK1 and NF-κB are involved in IRF1 regulation upon infection with a wide set of viral species." (PMID 34248923, 2021). "Upon infection, herpes simplex virus 1 (HSV-1) accessory protein Us11 prevents Hsp90 interaction with TBK1, disrupting Hsp90-TBK1 complex formation." (PMID 34966372, 2021). "To confirm that the effect of famotidine on the TBK1/IRF3 pathway is through TLR3-dependent signaling, we treated Caco2 cells with the TLR3 inhibitor CU-CPT 4a, which was added at the time of infection." (PMID 34214498, 2021). "In this study, we provide evidences that T. gondii requires activation of host TBK1/IRF3 and downstream genes (ISGs) expression for its efficient infection and growth in ARPE‐19 cells." (PMID 34464509, 2021). "Previous studies showed that infection of HEK293T cells with SeV enhanced the interaction of TRAF3 with both its upstream regulator MAVS and downstream effector TBK1." (PMID 33411856, 2021). "Consistently, the phosphorylation of TBK1, which is involved in the MDA5-mediated IFNβ induction, was increased in DOT1L-KO HD11 cells compared to that in WT cells at 24 h post-infection with ALV-J." (PMID 33363525, 2020). "A minimal increase in mycobacterial burden was detected in Mavs–/–BMMs as well as RIG-I, TBK1, IRF3 or IRF7-knockdown BMMs when compared to WT or control siRNA-treated cells at 72 hr post infection." (PMID 32463840, 2020). "A549 cells were pretreated with DMSO, MRT67307 HCl, a kinase inhibitor of TBK1 and IKKε, or Pyrrolidinedithiocarbamate ammonium, a selective NF-κB inhibitor, followed by BJ501 infection for 24 h." (PMID 32153544, 2020). "Contrary to the in vitro results, during infection of mice with SARS-CoV-2, an increase in IFN-α and TBK-1 was observed, with a peak at day 6 post-challenge, followed by a decrease in the expression of these molecules." (PMID 33362758, 2020). "In that study, Vpr promoted infection in macrophages and dendritic cells, despite HIV induced formation of innate immune signaling complexes containing TBK1, IRF3, and TRAF3, visualized by immunofluorescence staining." (PMID 33300875, 2020). "As shown by dual-luciferase assay, various degrees of decreased promoter activities of RLR signaling pathway key molecules, including RIG-I, IPS-1, STING, TBK1, and IRF7, were detected after VP4 overexpression under GCRV infection or when uninfected." (PMID 32268551, 2020). "FMDV Lpro cleaved TBK1 more efficiently than ERAV Lpro, consistent with the results observed during infection with FMDV or ERAV." (PMID 32667958, 2020).
infection (continued). "Upon infection, TRIM21 is derepressed by IKKβ and TANK-binding kinase 1 (TBK1)-mediated phosphorylation in the RING domain, promoting E2 binding, RING catalysis, NF-κB activation, and cytokine transcription." (PMID 31548319, 2019). "Both TBK1 and IRF3 are subsequently activated and, in response to this, a high level of beta interferon (IFN-β) was produced during NH/P68 infection; in contrast, Armenia/07 infection generated IFN-β levels below those of uninfected cells." (PMID 30918080, 2019). "Compared with the normal control group, the expression levels of all proteins (TLR3, TAK1, TBK1, IRF3, and IFN-β) were increased after infection with influenza virus." (PMID 31975996, 2019). "TBK1 plays a critical role as an integrator and inducer of RIG-I–MAVS, cGAS–STING, and TLR4–TRIF signaling pathways in response to infection by RNA viruses, DNA viruses, and bacterial LPS, respectively." (PMID 30769920, 2019). "Treatment with 5 μM BX795 (a pharmacological inhibitor of TBK1, also blocker of IFN-β) and siTBK1 increased the bacterial load of intracellular M. bovis in both J774a.1 and BMDM macrophages after 24 and 48 h of infection." (PMID 30042930, 2018). "We found that TBK1 silencing significantly decreased TBK1, p-TBK-1, and p-IRF3 expression in M. bovis infected J774a.1 cells at both 24 and 48 h post-infection." (PMID 30042930, 2018). "Influenza virus can be recognized by RIG-I during infection and activates type-I interferon production by signaling transduction from RIG-I, MAVS, and TBK1/IKK-ξ complex to IRF3." (PMID 28392790, 2017). "The phosphorylation of TANK-binding kinase (TBK1) and IRF3 was further increased in MDP-treated HCMV-infected cells compared to their levels in infection alone (lanes 3&4)." (PMID 26830977, 2016). "An interaction of SFTSV NSs with Tank-binding kinase 1 (TBK-1) was described, suggesting a potential mechanism for the deregulation of the interferon response during infection as TBK-1, a homolog of IKKɛ, activates both NF-κB and IRF-3." (PMID 24607799, 2014). "We found that infection with MVA-N1L virus induces lower levels of IFNA4 and IFNB mRNAs, as well as lower levels of p-TBK1 and p-IRF3." (PMID 24743339, 2014). "The small molecule DMXAA activates multiple immune pathways (NF-κB, TBK1/IRF3, NOD, and MAP kinase) but was ineffective as an antiviral unless it was administered before infection." (PMID 22574190, 2012). "Two hr after infection with Sendai virus, in vivo ubiquitinated forms of FLAG tagged TBK1 were affinity purified and analyzed by multi-dimensional liquid chromatography coupled with tandem mass spectrometry." (PMID 23028469, 2012). "TBK-1 is involved in IFN-β production after cytoplasmic recognition of L. monocytogenes, and IRF-7 is increased after infection and promotes an amplification loop of IFN-β production." (PMID 21610853, 2011). "Simultaneously or sequentially targeting TBK1 and IRF3 would be beneficial to MHV-A59 in spreading infection through effectively suppressing the type I IFN response." (PMID 21364999, 2011). "Expression of IRF3, TBK-1, IKKε, DDX3 or HSP90 remain unchanged by the presence of ICP0 during infection." (PMID 20454685, 2010). "Similar results were observed for endogenous TBK1 in the presence or absence of poly I:C stimulation or SVCV infection." (PMID 41532831, 2026). "This suggests that during the infection process of SVCV, SVCV-P has a high affinity for TBK1." (PMID 41363845, 2026). "Infection with the three clinically relevant strains, UAMS-1, HFH 29568, and TCH 1516, stimulated significant IFN-β production by osteoclasts, and such production was significantly reduced following TBK1/Ikkε inhibition." (PMID 40135931, 2025). "Moreover, AF-9 strain infection or poly (I: C) stimulation led to upregulation of the production of RIG-I, MDA5, MAVS, TRAF3, and TBK1 and phosphorylation of TBK1 and IRF3 in PAMs." (PMID 41012704, 2025).
infection (continued). "TBK1 is involved in the TLR-IRF3 signaling pathway in macrophages, and its downstream IFN-α/β signaling is critical for host defense against bacterial (group B Streptococcus, Pneumococcus, and Escherichia coli) infections." (PMID 40076567, 2025). "To further validate these findings, we knocked down Usp8 in Usp8fl/fl mouse embryonic fibroblast (MEF) cells via infection with Cre lentivirus and found that the EMCV‐induced expression of Ifnb1 and Cxcl10 and the EMCV‐induced phosphorylation of TBK1 and IRF3 were significantly impaired." (PMID 40525588, 2025). "To determine whether the IFN mRNA expression induced by TBK1 and IRF3 activation early in infection is regulated by RIG-I, we measured the effects of knocking out RIG-I." (PMID 39601535, 2025). "In addition, phosphorylation of TBK1 (pTBK1) and IRF3 (pIRF3) was observed in both the PRRSV-infected cell group and poly (I: C)-stimulated cell group at 12 h and 24 h post-infection." (PMID 41012704, 2025). "The transcript and protein levels of IFN-α, IFN-β, RIG-I, MDA5, MAVS, TRAF3, TBK1, and IRF3 in the PRRSV-infected cell group by anti-FcγRI IgG pre-treatment were significantly declined at 12 h and 24 h post-infection compared to those in the PRRSV-infected cell group by RNI pre-treatment." (PMID 41012704, 2025). "At 3 h post-SeV infection, HOIP, SHARPIN and TBK1 could all be found in complex with immunoprecipitated NEMO, enriched compared to mock-infected cells." (PMID 38001254, 2024). "Inhibitors for cGAS (RU.521), as well as TBK-1 (BX795), were used prior to infection." (PMID 39459875, 2024). "As a control, we verified that the TBK1 KD HEL cells were deficient in activation of downstream signaling as we did not detect p-TBK1 (Ser-172) after infection with an ICP0-null virus (ΔICP0) that has reduced ability to counteract type I IFN responses." (PMID 38470056, 2024). "We first utilized a mouse model to evaluate the roles of TBK1 and IRF3 during EV-A71 infection." (PMID 36626364, 2023). "Furthermore, the temporal expression profiles of eight selected antiviral-related mRNA including IRF3, IRF7, IKKβ, TBK1, IFIT1, IFI44, MX1 and ISG15 were detected by qRT-PCR, which showed a significantly stronger response at early infection under 20 °C." (PMID 37627029, 2023). "However, activation of TBK1 and IRF3 during EV-A71 infection was suppressed when STING was silenced." (PMID 36823147, 2023). "While we show that pSTAT1 depends on UL138 and USP1 at late times during infection in fibroblasts, we were surprised that neither total or phosphorylated levels of TBK1 were affected by UL138 or USP1 as a possible mechanism to sustain pSTAT1." (PMID 37289831, 2023). "Strikingly, type I IFN induction after infection was strongly diminished in cells expressing the kinase-dead TBK1 mutants K38A or S172A, in which IKKε upregulation does not take place." (PMID 36936901, 2023). "VP24, which is required for HSV’s viral capsid, can affect IFN-B production and block IRF3 activation by stopping the interaction between Tank binding kinase 1 (TBK1) and interferon regulatory factor 3 (IRF3) during infection, leading to the suppression of IFN expression." (PMID 38005873, 2023). "Finally, PIK3C2B, a positive regulator of autophagy, is identified as one of the key molecules mediating differential expression of TBK1 during ASFV-Δ110-9L/505-7R and ASFV-WT infection." (PMID 37162350, 2023). "We found that upon HSV-1 infection, the transcripts levels of TBK1 peak at 9 h post-infection in HEp-2 wt but not in PKR−/− cells." (PMID 37764935, 2023). "In addition, both TBK1 (phosphorylated at Ser172) and IRF3 (phosphorylated at Ser386) were activated in THP-1 cells after EV-A71 infection." (PMID 36823147, 2023). "Infection of HFFs with MVA resulted in STING and IRF3 phosphorylation that was markedly reduced in the absence of DNA-PKcs, indicating that DNA-PKcs is required for vaccinia virus-driven activation of the STING/TBK1/IRF3 signaling axis." (PMID 38269102, 2023).
infection (continued). "Subsequently, by assembling the STING-Tank-binding kinase 1 (TBK1)- interferon regulatory factor 3 (IRF3) signalosome, it activates the STING mediated signaling cascade, resulting in the stimulation of biological effects in response to infection." (PMID 35619707, 2022). "Gal3 silencing upon infection did not affect TBK1 phosphorylation while Gal8 silencing strongly reduced the TBK1 phosphorylation." (PMID 35857795, 2022). "Surprisingly, TBK1 was pre-activated in both TMEM41B KO and VMP1 KO cells prior to infection." (PMID 35939522, 2022). "Moreover, knockdown of UL13 in MEFs also enhanced phosphorylation of TBK1, IKKε, and IRF3, the downstream components of STING, and stabilized the protein levels of STING at 6 and 12 h post-infection of PRV." (PMID 35584187, 2022). "Upon infection with RNA viruses, TBK1 is activated by the upstream protein MAVS, and activated TBK1 recruits IRF3 and IRF7; these proteins undergo TBK1-mediated C-terminal phosphorylation to trigger their dimerization and nuclear translocation, an event followed by induction of IFN secretion." (PMID 34782737, 2021). "During the course of infection, single‐ or double‐stranded infectious RNAs from virus accumulated inside cells are recognized by PRRs, which recruit the kinase TANK‐binding kinase 1 (TBK1) and active IRF3 by phosphorylating its C‐terminal region." (PMID 34464509, 2021). "Upon infection, viral nucleic acids are recognized by PRRs, which subsequently recruit the adaptor protein of antiviral signaling protein to activate TANK-binding kinase 1 (TBK1)/inhibitor- nuclear factor kappa B kinase ε (IKKε)." (PMID 33909701, 2021). "Further analysis demonstrated that the inhibition of histone H2A nuclear/cytoplasmic trafficking could relieve the protein degradation of TBK1 and IRF3, and blocked the negative regulation of histone H2A on the SVCV infection." (PMID 34868031, 2021). "In order to explore whether CARMA3 regulates S. aureus-induced activation of the STING/TBK1/IRF3 pathway, we first sought to determine the mRNA and protein levels of CARMA3 following the infection." (PMID 33806598, 2021). "In addition to inhibiting the cGAS/STING/TBK1 pathway, UL138 suppresses transcription from the viral major immediate early promoter that drives productive infection, and reduces the generation of infectious progeny virions during latency." (PMID 34903048, 2021). "Additionally, confocal microscopy imaging revealed a co-localization of TRIM27 and TBK1 in the cytoplasm and nuclear export of TRIM27 in the late stage of infection." (PMID 34646390, 2021). "Notably, the extent of DNA-induced activation observed for STING, TBK1, and IRF3 during ECTVΔvSlfn and ECTV-vSlfnΔp26 infection was similar to that found in mock-infected cells, indicating that vSlfn is a critical inhibitor of cytosolic DNA sensing in ECTV." (PMID 32948585, 2020). "Furthermore, carvedilol increased the phosphorylation of TBK1, IRF3, IRF7, and STING and the dimerization and translocation of IRF3 after the infection." (PMID 33243993, 2020). "Moreover, PPP6C depletion also enhanced KSHV primary infection-induced IFN-β mRNA induction and phosphorylation of TBK1 and IRF3 in EA.hy926 cells compared to those in control cells." (PMID 32753499, 2020). "Conversely, ECTVΔvSlfn and ECTV-vSlfnΔp26 were completely impaired for such inhibition because infection with both mutant viruses showed notably high levels of STING, TBK1, and IRF3 phosphorylation and STING dimerization, indicative of activation of the cGAS-STING axis." (PMID 32948585, 2020). "Indeed, infection with EMCV-Lpro L92A, resulted in cleavage of eIF4G, as well as all other Lpro substrates (i.e. MAVS, TBK1, NF-κB p65 and G3BP1)." (PMID 32667958, 2020). "In addition, phosphorylation of MITA, TBK1, and IRF3 was increased following infection with HCMV-ΔUL42 compared to wild-type HCMV." (PMID 31107917, 2019).